SPATA31F3 (SPATA31 subfamily F member 3)
Synonyms: FAM205C; FAM205CP
Tractability: Antibody: UniProt predicts a signal peptide or a membrane-spanning region.
Gene: Protein-coding gene on chromosome 9 (34,889,066 to 34,895,764, reverse strand). Ensembl gene ENSG00000187791.
Subcellular location: Membrane
Gene Ontology:
Cellular component: membrane
Homologues: Orthologues: chimpanzee SPATA31F3 (97% identical), macaque FAM205C (94% identical), pig SPATA31F3 (64% identical), rabbit SPATA31F3 (62% identical), rat Spata31f3 (52% identical). Paralogues in human: SPATA31F1 (55% identical), SPATA31D1 (22% identical), SPATA31E1 (17% identical), SPATA31D3 (15% identical), SPATA31D4 (15% identical), SPATA31A6 (14% identical), SPATA31A1 (13% identical), SPATA31A3 (13% identical), SPATA31A5 (13% identical), SPATA31A7 (13% identical), SPATA31C1 (13% identical), SPATA31C2 (13% identical).